FAT1 (FAT atypical cadherin 1)
Diseases named in the same sentence as FAT1 in open-access papers (continued):
Sharing a sentence is not in itself a finding about the gene and the disease.
tumor (continued). "In cancers, FAT1 is found to have oncogenic as well as tumor suppressive role in context dependent manner." (PMID 31992226, 2020). "Despite the lack of identifiable recurrent mutations specific to either primary or metastatic tumours, single subclonal mutations in CITTA (OVA_048), DCC (OVA_048) and FAT1 (OVA_048) were all specific to primary tumours." (PMID 32099096, 2020). "We have previously identified a 4% and 29% mutation rate of Smad4 and Fat1 in HNSCC tissue samples, respectively, which are in agreement with the TCGA tumor database, the results of 4MOSCs analysis and the findings in present study." (PMID 33302499, 2020). "Loss of FAT1 hampers the formation of the multimeric Hippo signaling complex leading to unrestrained YAP activity and tumor progression." (PMID 31817001, 2019). "Among them, deletions in 4q (FAT1 and FBXW7) and 2q (TRIP12) affect genes that are frequently mutated in some cancer types, suggesting a tumour suppressor role of these ones." (PMID 29416628, 2018). "Overall, our oncogenomic and functional analyses support the role of FAT1 in cancer as a tumor suppressor acting upstream of YAP1." (PMID 29985391, 2018). "The FAT1 gene has been described as a tumour suppressor gene involved in Wnt/β-catenin signalling and frequently mutated in SCCs." (PMID 29416628, 2018). "This simplified our analysis by reducing the chance of potential functional compensation between FAT family members, making HNSCC the ideal tumor type to investigate FAT1 function." (PMID 29985391, 2018). "Taken together these data strengthen the association of FAT1 expression in CRC and other tumors and pave the way to the use of D8-FAT1 epitope in cancer immunotherapy, particularly in association with other tumor-specific epitopes." (PMID 30416985, 2018). "In the UM sample, these include the gene FAT1 which was found mutated in 33% (equally distributed among HPV+ and HPV− cases) and is known to be a tumor suppressor gene with somatic mutations in HNSCC as documented in COSMIC database." (PMID 30061624, 2018). "FAT1 is a tumor suppressor gene involved in the Wnt signaling, and FAT1 inactivation has been reported to promote tumor growth." (PMID 28506304, 2017). "Since FAT1 function in GC is poorly understood, we examined FAT1 expression in GC cell line, mouse model and tumor samples from GC patients." (PMID 29228735, 2017). "Further studies are now required to elucidate the mechanisms by which FAT1 contributes to tumor metastasis in GC." (PMID 29228735, 2017). "NOTCH1, CDKN2A, FBXW7, FAT1, and ZNF750 were considered as tumor suppressors and showed recurrent inactivating mutations." (PMID 29348864, 2017). "In the present study, we found that loss of FAT1 resulted in decreased cancer cell growth, and that FAT1 expression in tumor samples from GC patients and from a GC mouse model was highly up-regulated compared with that in normal gastric tissues." (PMID 29228735, 2017). "For example, the association between FAT1 mutation and overall survival in HNSCC differs according to the HPV status of the tumour, and loss of Caspase 8 not only has cell intrinsic effects but can also trigger inflammation." (PMID 27693639, 2016). "We show that loss of function mutations in FAT1 (an atypical cadherin) and CASP8 (Caspase 8) frequently occur in the same tumour." (PMID 27693639, 2016). "On analysis of tumorigenesis according to site of tumor and size of tumor, significantly decreased incidence of tumorigenesis was noted in the distal colon of fat-1 TG mice (P < 0.005) and these same mice displayed smaller tumor size (P < 0.005)." (PMID 27566583, 2016).
tumor (continued). "The expression levels of COX-2 and VEGF were similar, there were significant decreases in the oncogene COX-2 and VEGF, and significant increases in the expression of the tumor suppressive 15-PGDH in Fat-1 TG mice compared to WT mice." (PMID 27528223, 2016). "Additional mechanisms and significant induction of apoptosis in both tumor and non-tumor tissues were also noted in fat-1 transgenic (TG) mice." (PMID 27566583, 2016). "When inactivated, FAT1 is unable to sequester β-catenin at the cell membrane, which in turn promotes the activation of Wnt cascade and tumor growth." (PMID 26046463, 2015). "Lewis lung cancer (LLC) tumor cells implanted into Fat-1 mice showed slower growth, lower phospho-Akt levels, and higher levels of apoptosis and autophagy than cells implanted into wild-type mice." (PMID 26339598, 2015). "FAT-family proteins, including FAT1, FAT3, and FAT4, were found to be expressed in all examined tumor samples, including those with mutations." (PMID 25743105, 2015). "MYH9, 10 and 14 mutant tumors also exhibited mutational inactivation and/or copy loss of commonly altered tumor suppressors CDKN2A (p16), FAT1, or NOTCH1, and infrequently altered TGFβ pathway components, TGF-B-R2 or SMAD4." (PMID 26369831, 2015). "Although the cadherin gene FAT1 is likely to function as a tumor suppressor in OSCC, silencing its expression has been shown to exert only limited effects on the proliferation of OSCC cell lines." (PMID 25050621, 2014). "FAT1 is a tumour suppressor in Drosophila and an excellent candidate for having a similar role in humans." (PMID 24777035, 2014). "FAT1 and FAT4 suppress tumor growth through Hippo signaling activation, while FAT1 promotes tumor migration through actin polymerization at lamellipodia and filopodia." (PMID 23076869, 2012). "FAT1 is tumor suppressive or oncogenic in a context-dependent manner, while FAT4 is tumor suppressive." (PMID 23076869, 2012). "FAT1 and FAT4 suppress tumor growth via activation of Hippo signaling, whereas FAT1 promotes tumor migration via induction of actin polymerization." (PMID 23076869, 2012). "First, FAT1 has been described as one of the five tumor suppressor gene located on the long arm of chromosome 4 and was evidenced as an anti-proliferative factor of smooth muscle cells." (PMID 21406098, 2011). "We believe that with increasing research on FAT1, there will be new insights and strategies for understanding the role of FAT1 in the development and progression of hematologic and solid tumors, as well as in overcoming tumor drug resistance." (PMID 40242237, 2025). "FAT1 mutations often disrupt cell adhesion and polarity, promoting oncogenic signaling, while CASP8 alterations can impair apoptotic responses or, conversely, drive pro-inflammatory and pro-survival pathways within the tumor microenvironment." (PMID 41374467, 2025). "However, the expression pattern of FAT1 within stromal cells in the tumor microenvironment remains poorly characterized." (PMID 41230499, 2025). "Similarly, Hela cells or HNSCCs with suppressed MIB2 expression resembled FAT1 defective tumor cells showing faster proliferation in vitro as well as increased tumor growth in vivo compared to control cells." (PMID 40478800, 2025). "Together these results indicate that FAT1 expression promotes cell motility, which in a tumor context may reflect effects on cancer metastasis." (PMID 40083689, 2025). "Furthermore, under tumor-mimetic stiffness conditions, FAT1 silencing further enhanced focal adhesion formation, increasing both their quantity and size." (PMID 41230499, 2025). "Regarding the crucial role of FAT1 and its mutations in tumor progression and therapeutic prognosis, this study amalgamated 2,528 samples from 12 independent LUAD datasets to construct a molecular prognosis signature associated with FAT1 mutations." (PMID 40672387, 2025).
tumor (continued). "Targeting the FAT1-mediated signaling pathways may serve as a novel therapeutic strategy to inhibit tumor lymphatic metastasis." (PMID 41230499, 2025). "Finally, we compared in vivo tumor growth of the HNSCC CAL33 which lacks FAT1 with the CAL33 expressing the intracellular domain of FAT1." (PMID 40478800, 2025). "Given that downregulated FAT1 expression is associated with a poor prognosis in HNSCC patients, we wondered whether FAT1 could regulate the malignant behaviors of tumor cells." (PMID 39781458, 2025). "In conclusion, FAT1 expression was downregulated upon mutation in HNSCC, and its expression was negatively correlated with the poor prognosis of HNSCC patients, suggesting a tumor-suppressive role in HNSCC." (PMID 39781458, 2025). "Targeting tumor stiffness or FAT1-dependent pathways may represent promising strategies to suppress tumor-driven lymphangiogenesis and metastasis." (PMID 41230499, 2025). "FAT1-silenced and negative control (NC) mLECs were subsequently cultured on hydrogels mimicking physiological or tumor-associated stiffness." (PMID 41230499, 2025). "Collectively, these data suggested that high PCDHGB7 expression may promote a hybrid EMT state due to dysfunction of FAT1 protein, tumor stemness, and metastasis." (PMID 39949775, 2025). "Moreover, restoring ASCL2 or CPT1A expression in FAT1 KO SCC1 cells not only counteracted the reduction in cell proliferation and clonogenicity mediated by FAT1 KO, but also reversed the inhibition of tumor growth in an orthotopic mouse model." (PMID 40407216, 2025). "Notably, there was a significant reduction in tumor volume and a marked decrease in Ki67‐positive tumor cells in mice implanted with FAT1 KO cells compared to those with parental cells." (PMID 40407216, 2025). "Thus, suppression of YAP/TAZ activity and YAP/TAZ target gene activity by FAT1 is critical for its role as a tumor suppressor." (PMID 40478800, 2025). "FAT1 emerged as one of the top three mutant genes in HNSCC, with significantly higher mutation frequency in HPV‐negative (‐) tumor subtype compared with HPV‐positive (+) tumor subtype (20.08% vs. 0.76%) in TCGA HNSCC cohort." (PMID 40407216, 2025). "Restoring the tumor-suppressive function of FAT1 or enhancing Hippo pathway activity could offer novel strategies for treating cancers driven by YAP1 activation." (PMID 41256331, 2025). "Immunofluorescence analysis revealed that FAT1 knockdown increased both the number and area of FAs in mLECs on matrices with physiological stiffness, reaching levels comparable to those observed in the NC group cells grown on tumor-mimetic stiff matrices." (PMID 41230499, 2025). "Subsequent correlation analysis revealed a significant negative correlation between LVD and relative FAT1 fluorescence intensity, suggesting that reduced FAT1 expression in tumor-associated lymphatic vessels is associated with higher LVD." (PMID 41230499, 2025). "Future therapeutic strategies could aim to restore tumor-suppressive inputs (e.g., by targeting FAT1-mediated signaling or GPCRs that activate LATS1/2) or directly inhibit the oncogenic YAP/TAZ-TEAD axis." (PMID 41256331, 2025). "Moreover, the FAT1 knockdown group had fewer dead cells, indicating that FAT1 inhibition enhanced the antiapoptotic ability of tumor cells (green signifies living cells, whereas red denotes dead cells)." (PMID 39781458, 2025).
tumor (continued). "In addition, inhibition of FAT1 expression enhanced the sphere formation and colony formation abilities of tumor cells, and CSC-related markers were robustly expressed in the formed spheres." (PMID 39781458, 2025). "The results of this study indicate that FAT1 plays an anti-tumor role in DLBCL and may represent a novel target in the clinical treatment of DLBCL." (PMID 38782965, 2024). "FAT1 has been reported to reduce nuclear localization of Yes1 associated transcriptional regulator (YAP1) by maintaining Hippo pathway activity, thereby inhibiting tumor proliferation." (PMID 38782965, 2024). "In conclusion, this study reports the novel finding that FAT1 plays an anti-tumor role in DLBCL." (PMID 38782965, 2024). "FAT1 is able to regulate tumor cell stemness through Hippo-independent pathways." (PMID 37147285, 2023). "FAT1 has two opposing mechanisms, on the one hand, binding ß-catenin to prevent tumor progression." (PMID 36969232, 2023). "Still, other studies suggest that FAT1 may induce or inhibit cancer cell migration and invasion of the same tumor type in a context-dependent manner." (PMID 37371091, 2023). "In HPV-negative (HPV-) HNSCC, the FAT1 mutation rate is as high as 28% with many truncation and nonsense mutations, suggesting that wild-type FAT1 serves as a tumor suppressor gene in this disease." (PMID 35965328, 2022). "FAT1 functions as a tumor suppressor or promoter, depending on the variety of cancer." (PMID 34939311, 2022). "The FAT1 gene functions as a tumor suppressor or promoter and remains incompletely understood." (PMID 34939311, 2022). "However, compared to the ample studies and information available of FAT1 over the past two decades, the role of FAT1 in tumor initiation and progression has been conflicting." (PMID 35646625, 2022). "FAT1, a tumor suppressor recurrently inactivated in ESCC, could dampen the activity of the Hippo effector YAP." (PMID 35993362, 2022). "We found a significant association between FAT1 mRNA level and EMT phenotype-related marker genes in almost all tumor types, implying that FAT1 may play a role in the EMT phenotype in other tumors." (PMID 36517565, 2022). "Next, knocking down the FAT1 expression showed that downregulated FAT1 could inhibit tumor formation and progression by inhibiting cell proliferation, stemness, and cell cycle and promoting the apoptosis." (PMID 35646625, 2022). "Also, intravenous injection of EPCAM+Fat1-cKO tumor cells gave rise to a higher number of lung metastases as compared to tumor cells with wild-type FAT1, which clearly illustrated that deletion of FAT1 promotes metastasis in vivo." (PMID 35965328, 2022). "In order to find a probable link between FAT1 expression in tumor samples and immune cell infiltration levels as indicated by TIMER2.0 results, we checked for any association between the expression of FAT1 and that of known immunosuppressive cytokines, TGF-β1 and TGF-β2." (PMID 35720420, 2022). "Two tumor suppressor genes NOTCH1 and FAT1 both have a high nonsense mutation rate in HNSCC." (PMID 36428516, 2022). "Consequently, we found that using an in vitro THP-1 monocyte chemotaxis model that decreased TGF-β1/TGF-β2 production by FAT1-depleted tumor cells led to increased migration of THP-1 monocytes toward supernatants of siFAT1-treated cells." (PMID 35720420, 2022). "Furthermore, PD1 that mediates the immune escape of tumor cells is downregulated in the tumor microenvironment with mutant FAT1, leading to tumor immunotolerance." (PMID 35573184, 2022). "Thus, we found a relative decrease in TGF-β1 secretion from FAT1-depleted tumor primary cultures and other studied cancer cell lines." (PMID 35720420, 2022). "Furthermore, FAT1 exhibited moderate classification ability between the tumor tissues and normal tissues lesion types with an AUC = 0.78 in HNSC and an AUC = 0.804 in OSCC." (PMID 35646625, 2022). "Here, we have studied the role of FAT1 in tumor immune suppression." (PMID 35720420, 2022).
tumor (continued). "Therefore, our current study provided a reason for FAT1 to jump out of its classic role as a tumor suppressor by featuring its oncogenic properties mainly via cellular proliferation and repair." (PMID 35646625, 2022). "As tumor-suppressor genes, the inactivation of FAT1 and NOTCH1 may converge to inhibit the Wnt/β-catenin signaling pathway, which is implicated in the deregulation of cell polarity and differentiation." (PMID 34194478, 2021). "We found that drinking status was associated with TMB and frequent FAT1 and ADAM29 mutations, implying that lifestyle factors might shape different mutational landscapes and the tumor biology of ESCC." (PMID 34885197, 2021). "Besides, a previous study has suggested that FAT1 is a tumor suppressor or has carcinogenic effects and participates in the regulation of cell metastasis, but this study demonstrates that FAT1 mutation contributes to the favorable OS for DLBCL patients." (PMID 33722306, 2021). "FAT1 inhibits tumor progression by activating Hippo signaling." (PMID 34421348, 2021). "For instance, in oesophageal squamous cell carcinoma, depletion of E2F-1 may accelerated tumour cell migration in vitro by downregulating FAT1 expression." (PMID 34461908, 2021). "Loss of FAT1 results in an accumulation of HIPPO pathway transcription factors that induce overexpression of CDK6, which in turn increases the growth inhibitory concentration of CDK4/6i, allowing tumours to proliferate." (PMID 33671468, 2021). "Hence, a deeper delve into GPC3-FAT1 interaction is expected to address the missing link between FAT1 expression level and the molecular mechanisms that drive mesenchymal phenotype of tumor cells." (PMID 33878524, 2021). "Similar to the previous reporting the driver genes in CC, FBXW7, EP300, CASP8 and FAT1(10%, 20%, 10% and 10% of tumor, respectively) were also identified in our cohort with a low frequency, which may result from a small sample size in our cohort." (PMID 34221990, 2021). "Furthermore, both GPC3 and FAT1 regulated the expression of tumor metastasis-related genes, e.g., Snail, Vimentin, and E-Cadherin." (PMID 33420124, 2021). "FAT1 often functions as a tumor-suppressor or oncogene in different types of human cancer." (PMID 34712552, 2021). "Mutations in FAT1 and KEAP1 generated several complex tumor antigens and higher TMB, but as the expression of many immune-related genes was significantly lower, it may lead to immune escape or poor efficacy of ICBs." (PMID 33808631, 2021). "The human FAT1 and FAT3 gene encode large proteins with extracellular cadherin repeats that are associated with neurodevelopment and cell migration and are most homologous, which involved in tumor suppression." (PMID 32209061, 2020). "All these results suggested that FAT1 could be used as a novel candidate tumor suppressor or prognostic predictor." (PMID 31141819, 2019). "The present study thus provides rationale to look outside the box of classical and traditional classification of FAT1 as a tumor suppressor, by highlighting various oncogenic properties that make FAT1 a putative therapeutic target that should not be underestimated in OSCC." (PMID 31783581, 2019).